ENSG00000283201 (novel protein)
Gene: Protein-coding gene on chromosome 19 (23,222,755 to 23,274,221, reverse strand). Ensembl gene ENSG00000283201.
Genetic constraint (gnomAD): Loss-of-function variants: 3 observed, 5.26 expected, observed/expected ratio (o/e) 0.57, 90% interval 0.26 to 1.44. That is too few expected variants to judge how well the gene tolerates losing a copy. Missense variants: 103 observed, 98.43 expected, observed/expected ratio (o/e) 1.05, 90% interval 0.89 to 1.23. Synonymous variants: 37 observed, 32.38 expected, observed/expected ratio (o/e) 1.14, 90% interval 0.88 to 1.5.